C5orf34 (chromosome 5 open reading frame 34)
Synonyms: FLJ32363
Tractability: PROTAC: ubiquitination databases record sites on it.
Gene: Protein-coding gene on chromosome 5 (43,486,709 to 43,515,148, reverse strand). Ensembl gene ENSG00000172244.
Genetic constraint (gnomAD): Loss-of-function variants: 20 observed, 33.05 expected, observed/expected ratio (o/e) 0.61, 90% interval 0.43 to 0.88. The upper end of that interval is the gene's LOEUF score, 0.88, which puts it in group 3 of 6, group 1 being the genes least tolerant of losing a copy. Missense variants: 390 observed, 426.52 expected, observed/expected ratio (o/e) 0.91, 90% interval 0.84 to 0.99. Synonymous variants: 139 observed, 145.67 expected, observed/expected ratio (o/e) 0.95, 90% interval 0.83 to 1.1.
Homologues: Orthologues: chimpanzee C5H5orf34 (99% identical), macaque C6H5orf34 (95% identical), dog C5orf34 (84% identical), pig C5orf34 (78% identical), guinea pig C5orf34 (77% identical), mouse 4833420G17Rik (75% identical), rat C2h5orf34 (74% identical), rabbit C5orf34 (72% identical), zebrafish si:dkeyp-118g6.3 (31% identical).
Diseases named in the same sentence as C5orf34 in open-access papers:
C5orf34 is named in the same sentence as 21 diseases in open-access papers, as found by Europe PMC text mining. Sharing a sentence is not in itself a finding about the gene and the disease. The quoted sentences say what the papers report.
breast carcinoma (1 paper, 2023). "C5orf34, on the other hand, was shown to be less expressed in several malignancies, including leukemia, prostate cancer, lymphoma, breast cancer, ovarian cancer, and central nervous system cancer." (PMID 38078888, 2023). "However, in several other datasets, there were lowered C5orf34 levels in some cancers, including breast cancer, leukemia, lymphoma, ovarian cancer, brain, and central nervous system cancer, prostate cancer, and other cancers." (PMID 38078888, 2023).
gynecologic cancers (1 paper, 2023). "Immunohistochemical staining confirmed the findings that C5orf34 expression was remarkably up-regulated in a variety of gynecologic cancers." (PMID 38078888, 2023).
cancer (2 papers, 2011 to 2023). A tumor composed of atypical neoplastic, often pleomorphic cells that invade other tissues. "Theremaining three genes NAT13, MUM1L1,C5orf34, however, have yet to be investigated in any cancer toour knowledge thus validating our approach for the purposes of identifying novelovarian cancer-associated genes." (PMID 21423607, 2011). "Moreover, we discovered that C5orf34 was associated with Th2 cells in a positive manner in several cancers, including ACC, KICH, BLCA, SKCM, and LIHC." (PMID 38078888, 2023). "To begin, we used the independent GTEx, TCGA, and Oncomine databases for the purpose of acquiring data on the C5orf34 expression in 33 distinct cancers." (PMID 38078888, 2023). "The potential relationship between pan-cancer prognosis and C5orf34 variation was then further investigated." (PMID 38078888, 2023). "With the aid of the data from TCGA database, the link between C5orf34 expression level and pan-cancer prognostic value was then explored." (PMID 38078888, 2023). "C5orf34 has a malignant biological characteristic and complex prognostic value for pan-cancer, according to these findings." (PMID 38078888, 2023). "C5orf34 is also strongly expressed in several cancers and is related to an unfavorable prognosis, although the precise molecular mechanism behind this effect has not been determined." (PMID 38078888, 2023). "In various cancers, the expression of C5orf34 has a positive correlation with the high presence of immune infiltrates, particularly the T cell follicular helper, Th2 cells, and Tregs." (PMID 38078888, 2023). "In most cancers, the count of C5orf34 in tumor tissues was much greater than in normal tissues, which was in line with our earlier findings." (PMID 38078888, 2023). "In this study we found that C5orf34 expression differed significantly among cancers types, according to the findings." (PMID 38078888, 2023). "The expression level of C5orf34 was found to be elevated in several cancers, and this high expression is highly related to poor survival in most tumors." (PMID 38078888, 2023). "In the vast majority of malignancies, there was a positive correlation between the immune-related genes and C5orf34 expression." (PMID 38078888, 2023). "We used the Oncomine database for the purpose of examining C5orf34 expression in cancer tissues and normal tissues and discovered that its expression was notably higher in cancers than in healthy tissues." (PMID 38078888, 2023). "Except for PAAD and OV, we discovered that most cancer tissues contained lower C5orf34 methylation levels in comparison to the normal tissues." (PMID 38078888, 2023). "With the exception of OV and PAAD, the majority of cancer tissues had lower C5orf34 methylation levels than normal tissues." (PMID 38078888, 2023). "Eventually, we discovered that C5orf34 expression has a close relationship with the prognosis of patients with cancer, which may open up new avenues for clinical research." (PMID 38078888, 2023). "In addition to THCA and PRAD, C5orf34 expression was found to be significantly elevated in the majority of cancers." (PMID 38078888, 2023). "Furthermore, increased C5orf34 methylation levels were correlated with a favorable patient prognosis in several cancer patients." (PMID 38078888, 2023). "Notably, we discovered that C5orf34 SNV was closely related to patient prognosis in a variety of cancers." (PMID 38078888, 2023). "Furthermore, several cancer patients who had elevated C5orf34 methylation levels had better prognoses, including MESO, UCEC, LIHC, CHOL, UVM, GBM, and PRAD." (PMID 38078888, 2023). "Finally, our data corroborate the role of C5orf34 expression in tumor prognosis and provide fresh information about cancer treatment choices." (PMID 38078888, 2023). "Furthermore, C5orf34 expression differed by race in 5 cancers types including LIHC, UCEC, BRCA, ESCA, and ACC." (PMID 38078888, 2023). "Following that, we delved into C5orf34 methylation in pan-cancer." (PMID 38078888, 2023).
cancer (continued). "With the aid of the independent GTEx, TCGA, and Oncomine databases, we examined the C5orf34 expression in 33 distinct cancer types in the present research, demonstrating significant disparities in a pan-cancer expression of C5orf34 between normal and tumor tissues." (PMID 38078888, 2023). "Moreover, in pan-cancer, we intensively explored C5orf34’s predictive relevance." (PMID 38078888, 2023). "In nearly all cancer types, the correlation coefficients between TMB, MSI, and C5orf34 were consistently below 0.6." (PMID 38078888, 2023). "In most cancer such as STAD, THYM, UVM, and OV, C5orf34 was shown to have a positive correlation with T cell follicular helper, as well as a positive correlation with Tregs in LIHC and THYM." (PMID 38078888, 2023). "Although some data suggest that chromosome 5 open reading frame 34 (C5orf34) plays a pivotal part in the onset and disease progression of various cancers, there is no pan-cancer investigation of C5orf34 at present." (PMID 38078888, 2023). "In order to elucidate C5orf34’s immunomodulatory influence in the tumor microenvironment, we investigate the co-expression connection between immune-related genes and C5orf34 (including chemokine ligands, immune inhibitors, MHC, and chemokine receptors, and immunostimulators) in pan-cancer." (PMID 38078888, 2023). "In many cancers, including THYM, STAD, UVM, and OV, T cell follicular helper cells displayed a positive correlation with C5orf34, except in the case of DLBC, where a negative correlation was observed." (PMID 38078888, 2023).
tumor (1 paper, 2023). "With the aid of the R software, we intensively explored the association of patients’ prognoses with the expression level of C5orf34 as well as its possible function in tumor immunity." (PMID 38078888, 2023). "Despite the fact that this study verified the role of C5orf34 in tumor formation and patient prognosis, certain levels of limitations remained." (PMID 38078888, 2023). "In addition, we discovered a correlation between C5orf34 expression and immune cell infiltration, prognosis, clinical features, tumor microenvironment, and immunotherapy indicators (TMB, MSI) in the present research." (PMID 38078888, 2023). "There is a correlation between C5orf34 expression and TMB, tumor immunity, tumor microenvironment, and MSI; however, there isn’t enough evidence to prove it." (PMID 38078888, 2023). "The immunotherapy indicators, immune cell infiltration, and tumor microenvironment (TMB, MSI) have a correlation with the expression level of C5orf34." (PMID 38078888, 2023).
C5orf34 also shares sentences with these, for which no sentence is quoted: bladder cancer (1 paper); central nervous system cancer (1); cervical cancer (1); colorectal cancer (1); esophageal cancer (1); gastric cancer (1); head and neck cancer (1); kidney cancer (1); leukemia (1); liver cancer (1); lung carcinoma (1); lymphoma (1); melanoma (1); ovarian carcinoma (1); pancreatic cancer (1); prostate carcinoma (1); sarcoma (1).